INS (insulin)
Diseases named in the same sentence as INS in open-access papers (continued):
Sharing a sentence is not in itself a finding about the gene and the disease.
diabetes (continued). "We restricted our recruitment to normoglycemic and non-obese subjects and it remains possible that people with glucose intolerance or frank diabetes may respond differently, due to effects of chromium on insulin secretion or glucose toxicity." (PMID 23194380, 2012). "Recently, studies have found that preptin enhances insulin secretion in rats and might play a role in the pathogenesis of diabetes and PCOS in humans." (PMID 22309801, 2012). "However, if insulin production cannot match the increased demand imposed by insulin resistance, hyperglycemia and frank diabetes ensues." (PMID 22253604, 2012). "No individual factor could predict final HbA1c ≥7%, except for age at diabetes onset (OR: 0.963; 95%CI 0.930–0.997; p=0.033) and insulin use at baseline (OR: 3.412; 95%CI 1.110–10.491; p=0.032)." (PMID 23171858, 2012). "Diabetes-associated NEFA patterns indicate increases in SCD activity and decreases in VLCPUFA chain shortening, which may indicate impaired hepatic insulin sensitivity and/or fatty liver disease." (PMID 23144998, 2012). "Thus, a balance between glucose control to avoid diabetes progression and insulin sensitivity to avoid cirrhosis complications is required." (PMID 23166628, 2012). "These include T2DM patients who cannot adequately control their diabetes with oral therapy, and who have considerable obesity, or where hypoglycaemia and/or weight gain is particularly problematic or for whom therapy with insulin would have significant occupational implications." (PMID 22051096, 2012). "In particular, the capacity of hBSCs to differentiate into insulin-producing cells may hold great promise for the development of personalized treatments for diabetes." (PMID 22865647, 2012). "Indeed, PPARγ agonists are routinely used for the treatment of patients with diabetes or hyperglycemia and it is established that activation of PPARγ ameliorates insulin sensitivity in vivo and ex vivo." (PMID 22407012, 2012). "The patients with diabetes and strict administration of insulin during the experiment only marginally differed from healthy controls with respect to the plasma glucose concentration while their plasma insulin concentration was significantly higher." (PMID 23051145, 2012). "Self-efficacy/empowerment was assessed using Self efficacy-plate model; Diabetes empowerment scale; Self efficacy scores for diet, exercise, self-monitoring, oral glycaemic agents, insulin; Confidence to overcome challenges and Sallies self-efficacy for diet and exercise." (PMID 22824531, 2012). "Diabetes is classified as a group of chronic metabolic disorders that are characterized by elevated blood glucose levels due to the insufficient production of insulin and/or peripheral insulin resistance." (PMID 22523676, 2012). "Recent meta-analyses have shown that elevated insulin and glucose concentrations in persons without diabetes were associated with an increased cardiovascular disease risk." (PMID 23300589, 2012). "However, the Diabetes Control and Complications Trial (DCCT) also showed that strict glycemic control with intensive insulin management is associated with an increased risk of severe hypoglycemic events when compared to conventional treatment." (PMID 22716962, 2012). "In diabetes, the increased blood sugar levels might be due to either insulin resistance of the body cells or decreased secretion of insulin from β-cells manifested in the decreased serum insulin levels." (PMID 22593683, 2012). "Fasting insulin, a marker of insulin resistance, was tested but did not result in significant improvement in diabetes risk prediction." (PMID 22615828, 2012). "This excessive pyruvate is converted to lactate for which LDH is needed and there fore the activity of LDH may be increased due to less insulin availability in diabetes." (PMID 24250450, 2012).
diabetes (continued). "Beside the presence of commercially available oral antidiabetic drugs and insulin injections for the treatments of both type I and II diabetes, a vast scientific data is available which describe that variety of herbs are used as effective hypoglycemic agents with different modes of action." (PMID 23365565, 2012). "Recently the study in our laboratory showed that trigonelline had a beneficial effect for diabetes through decreasing blood glucose and lipid levels, increasing insulin sensitivity index and insulin content, upregulating antioxidant enzyme activity, and decreasing lipid peroxidation." (PMID 23304193, 2012). "Additionally, the insulin-secretory reserves of the pancreatic remnant are typically sufficient to prevent postsurgical diabetes." (PMID 22385578, 2012). "Thus, the enrolled patients were obese Japanese subjects, had relatively long duration of diabetes, and most of them were treated with insulin, but had preserved insulin secretion capacity." (PMID 22973968, 2012). "Thiazolinediones are a class of insulin sensitizing drugs widely used to control diabetes." (PMID 22401035, 2012). "Absolute or relative lack of insulin or insulin action is a hallmark of diabetes, and defective insulin action in the skin has been proposed as an important mechanism contributing to wound healing defects in this disease." (PMID 22662132, 2012). "For many with insulin treated diabetes and their families, the ability to measure blood glucose immediately is one of the essential management tools, enabling them to confirm suspected hypoglycaemic episodes or high glucose values rapidly and to take corrective action." (PMID 22416896, 2012). "Besides impaired pancreatic functioning, peripheral insulin resistance in adipose tissue, the liver, and muscle tissues are the pathophysiological hallmarks of this type of diabetes." (PMID 22523676, 2012). "However, based on our analysis, these defects seem insufficient to explain the onset of diabetes, which occurs only when a rapid, marked deterioration in insulin sensitivity occurs, in correspondence with the rise of glucose levels." (PMID 23185618, 2012). "The influence of insulin on the development of vascular complications in diabetes is still unclear." (PMID 22262970, 2012). "Mitochondrial dysfunction in insulin target tissues such as liver and muscle could result in insulin resistance and diabetes." (PMID 22230186, 2012). "Interestingly, while a reduction of insulin/IGF-I signaling can result in diabetes, its reduction can also increase longevity and delay the onset of protein-aggregation-mediated toxicity." (PMID 23211425, 2012). "Deficiencies of specific vitamins and minerals that play important roles in glucose metabolism and insulin signaling pathways may contribute to the development of diabetes in the obese population." (PMID 22462011, 2012). "The low affinity of the FLI≤20 group for diabetes manifestation might be explained by their comparable level of insulin sensitivity to the NGT participants of the study." (PMID 22393439, 2012). "The reasons for these inconsistencies are not clear at the present time, but may relate to differences in insulin resistance, extent of obesity, and the duration and severity of diabetes seen in mice." (PMID 22474596, 2012). "In our population there were only n = 7 people with diabetes and we couldn't confirm that reducing body weight and decreasing insulin resistance only will help to increase urinary pH." (PMID 22550482, 2012). "In 60 middle-aged individuals without diabetes we studied the associations of fasting plasma glucose, 2-hour post oral glucose tolerance test plasma glucose, insulin sensitivity as well as body fat percentage with CVD risk." (PMID 22720085, 2012). "The main mechanisms of diabetes in IEM involve either defects of insulin secretion or insulin resistance, which might be promoted by liver or muscle involvement and estrogen deficiency." (PMID 22284844, 2012).
diabetes (continued). "Following the 2-year diabetes self-management support intervention, we found significant improvements for following a healthy diet (P = .03), spacing carbohydrates evenly across the day (P = .005), using insulin as recommended (P = .047), and achieving diabetes-specific quality of life (P = .02)." (PMID 22677159, 2012). "Severe hypoglycaemia still represents a significant problem in insulin-treated diabetes." (PMID 22727048, 2012). "A recent study in mice showed that mutations in the genes encoding the CLOCK and BMAL1 transcription factors resulted in impaired glucose tolerance, reduced insulin secretion and defects in islet development, while ablation of the endogenous pancreatic clock resulted in the development of diabetes." (PMID 22485135, 2012). "Medicines used for treating diabetes were insulin and metformin, and, for hypertension the most frequent medicine used was methyldopa followed by others with low frequencies classified as “unknown risk”." (PMID 23346403, 2012). "Prescriptions for insulin and oral anti-diabetic agents were used as proxies for diabetes mellitus." (PMID 23186328, 2012). "Findings of the meta-analysis indicated that compared with non-glargine insulin use, insulin glargine use was associated with a 19% reduced odds of overall cancer in patients with diabetes." (PMID 23284776, 2012). "Besides, GLUT4 levels have been shown to be increased in the cerebellum of db/db mice and decreased in STZ induced diabetic rats, suggesting insulin sensitive GLUT4 expression in two different models of diabetes." (PMID 23202918, 2012). "Manipulation of MCU activity, in particular, may thus provide potential strategies to improve defective insulin secretion in some forms of diabetes." (PMID 22829870, 2012). "Patients with a history of poor glycaemic control, such as F4, explained how this motivation arose from a perception that flexible intensive insulin therapy offered a more “logical process” for managing her diabetes than her previous regimen comprising two fixed daily doses of insulin." (PMID 22891794, 2012). "Problems related to complexity of insulin therapy such as determining insulin type and dose were not often observed, which may be due to sufficient experience of using insulin and comprehensive knowledge of diabetes and insulin in this group." (PMID 22719830, 2012). "In this well-characterized case–control study in a Japanese population, we identified SHBG levels in women and total and free testosterone levels in men to be inversely associated with diabetes after multivariable adjustment for FLI and fasting insulin as well as known risk factors for diabetes." (PMID 23066943, 2012). "In diabetes, this network control is disrupted by deficiency or absence of insulin secretion and/or insulin resistance, which has to be compensated by technological means." (PMID 24278682, 2012). "In chemically induced study, since the treatment with AG490 was started one week after diabetes onset, beta-cell destruction was more or less completed at this stage; therefore, improvement in blood glucose level is the result of increased insulin sensitivity by AG490." (PMID 22615750, 2012). "We reasoned that an unbiased search for regulators of insulin production might reveal new diabetes drug targets." (PMID 22253604, 2012). "In people with type 2 diabetes (the most common form of diabetes), blood sugar control fails because the fat and muscle cells that usually respond to insulin by removing excess sugar from the blood become less responsive to insulin." (PMID 22509138, 2012). "However, as with most gastric bypass patients with preexisting diabetes, her insulin sensitivity tremendously improved after gastric bypass to the point where she no longer required treatment with insulin." (PMID 22937294, 2012). "While KU-32 did not spare islets from the degradation associated with diabetes, it did maintain a statistically higher level of insulin per β-cell." (PMID 23197975, 2012).
diabetes (continued). "Chronic alcohol abuse leads to insulin and IGF resistance in target organs, including liver, brain, and placenta, and it is also associated with peripheral insulin resistance, mimicking effects of Type 2 diabetes mellitus." (PMID 23016132, 2012). "Interventions which preserve endogenous insulin secretion may therefore improve control and prevent complications in patients with T1D." (PMID 22807927, 2012). "Eleven patients had insulin treated diabetes mellitus when the study began." (PMID 23346184, 2012). "HP eradication was significantly increased with age, male sex, diabetes status, insulin use, use of calcium channel blocker, panendoscopic examination, hypertension, dyslipidemia, chronic obstructive pulmonary disease, stroke, nephropathy, ischemic heart disease and peripheral arterial disease." (PMID 22571603, 2012). "At contrast, mean insulin and C-peptide values during the OGTT, and total insulin secretion, were not significant predictors of diabetes risk (P>0.15)." (PMID 23185618, 2012). "Due to its multidimensional nature, ANN has also been used for diagnosis of diabetes based on physical parameters, prediction of blood glucose levels, regulation of insulin dosage setting algorithms for insulin pumps and detection of hypoglycemic episodes in type I diabetes patients." (PMID 22952998, 2012). "Even in established cases of diabetes mellitus, curcumin has demonstrated hypoglycemic effects via reversal of gluconeogenic enzymes, reducing levels of glycosylated hemoglobin (HbA(1C)), and increasing plasma insulin, glycogen, and C-peptide." (PMID 22329651, 2012). "Both the direct and the indirect maternal and neonatal benefits demonstrated that pregnant women with diabetes or mild hyperglycemia treated with diet and insulin therapy were less likely to achieve glycemic control, and therefore benefited less than those managed in an outpatient setting." (PMID 22344355, 2012). "In this sense, the endocrine dysfunction of the gland as the impairment of insulin production triggers the development of type 2 diabetes mellitus (T2DM) therefore, resulting in an abnormal regulation of blood glucose concentration with ulterior significant complications." (PMID 23162532, 2012). "A companion focusing on non-insulin diabetes agents will follow in the next issue of JCHIMP." (PMID 23882369, 2012). "Median diabetes duration was 4.4 years and 22% of participants reported to use insulin." (PMID 22927948, 2012). "Further controlling for fasting insulin levels did not materially alter the results in our study, but use of sulphonylurea or insulin among participants with diabetes might have influenced the insulin levels." (PMID 23066943, 2012). "There are many reports indicating that ER stress plays an important role in the impairment of insulin biosynthesis, suggesting that reduction of ER stress could be a therapeutic target for diabetes." (PMID 22474424, 2012). "Deficiency of insulin or insensitivity of its receptors can result in persistent or recurrent hyperglycemia, leading to a chronic noncommunicable disease called diabetes mellitus." (PMID 22851968, 2012). "This defect when superimposed for an increased need for insulin, could contribute to impaired glucose homeostasis, glucose intolerance and diabetes." (PMID 22675349, 2012). "Limitations of our study include that we have recruited participants with a mixture of Type 1 and Type 2 diabetes and that differences seen may reflect differences in insulin secretion between the two diabetes subtypes." (PMID 22681724, 2012). "This platform provides health care services to diabetes patients and caregivers using new chronic care models that support separation of activity spaces of the information care space where a closed-loop system is implemented for managing and treating diabetes and for delivering insulin." (PMID 23612026, 2012).
diabetes (continued). "In that study, diabetes onset is due to a marked decline in beta-cell function, occurring in a relatively short time, accompanied by hyperglycemia, on a background of progressive decline in insulin sensitivity." (PMID 23185618, 2012). "Also in this model, MSC were able to differentiate into insulin-producing cells releasing insulin in a glucose-dependent manner and improving the natural history of diabetes." (PMID 21822425, 2012). "The low relative folding rate and plentiful insulin precursor manufactured in β-cells make PIHO susceptible to genetic and environmental influences, and PIHO disorder has been critically linked to defects in β-cells in diabetes." (PMID 22470529, 2012). "Hypoglycemia is a common complication of insulin treatment in type 1 diabetes mellitus." (PMID 22716962, 2012). "Finally, we will briefly discuss the pros and cons of the potential therapeutic interest of insulin in diabetes- and age-related neurodegeneration." (PMID 22500228, 2012). "Diabetes mellitus (DM) describes a metabolic disorder of multiple etiologies characterized by chronic hyperglycemia with disturbances of carbohydrate, fat, and protein metabolism resulting from defects in insulin secretion, insulin action, or both." (PMID 22162811, 2012). "Even for diabetes, insulin, which has been the main glucose lowering treatment, has been evaluated in combination with recombinant human insulin-like growth factor I (IGF1), a pathway that if restored can lead to much higher glucose lowering than insulin alone." (PMID 23210531, 2012). "These were not significantly altered, but did trend towards lower levels in offspring of maternal diabetes than in controls, suggesting that insufficient insulin production may contribute to the phenotype." (PMID 23209676, 2012). "The results of clinical trials that administer high doses of high bioavailability chromium suggest that supplementation with chromium may improve insulin resistance and glycemic control in diabetes." (PMID 22462011, 2012). "A lower proportion of patients initiating exenatide b.i.d. had microvascular and macrovascular complications (compared with patients initiating insulin), a finding that might reflect their younger mean age, glycemic control (HbA1c), and duration of diabetes." (PMID 22714818, 2012). "Diabetes, characterized by persistent elevation of blood glucose levels (hyperglycaemia), occurs due to inadequate production of insulin (type 1 diabetes; T1D), or resistance to endogenous insulin usually associated with the metabolic syndrome and obesity (type 2 diabetes; T2D)." (PMID 22013533, 2012). "The need for insulin treatment is common, but the diabetes is usually easy to control." (PMID 22284844, 2012). "Thus, T1D is characterized by insulin insufficiency and is treated by exogenous insulin administration, hence, its former definition as an insulin-dependent type of diabetes." (PMID 22235232, 2012). "Insulin-dependent type 1 and non-insulin dependent type 2 are the two main types of diabetes." (PMID 22780954, 2012). "Patients with diabetes may be asked to delay their diabetes medication or insulin dose until the test is completed." (PMID 22257465, 2012). "The situation is often exacerbated by the fact that adolescents are expected to assume increasing responsibility for their own diabetes care with subsequent decreased supervision by caregivers for blood glucose monitoring, insulin administration and dose adjustment." (PMID 22672865, 2012). "Our results suggest that insulin may play a significant role in the regulation of microvascular perfusion in patients with diabetes through its vasodilation effect." (PMID 22262970, 2012). "Patients perceive that their diabetes is advanced once they are advised to start insulin therapy." (PMID 22469132, 2012).